STRN (striatin)
Description:
Calmodulin-binding scaffolding protein which is the center of the striatin-interacting phosphatase and kinase (STRIPAK) complexes. STRIPAK complexes have critical roles in protein (de)phosphorylation and are regulators of multiple signaling pathways including Hippo, MAPK, nuclear receptor and cytoskeleton remodeling. Different types of STRIPAK complexes are involved in a variety of biological processes such as cell growth, differentiation, apoptosis, metabolism and immune regulation (Probable).
Synonyms: PPP2R6A; STRN1; SG2NA
Tractability: Antibody: UniProt places it where antibodies can reach, with medium confidence. PROTAC: ubiquitination databases record sites on it; its protein half-life has been measured.
Gene: Protein-coding gene on chromosome 2 (36,837,698 to 36,966,625, reverse strand). Ensembl gene ENSG00000115808.
Subcellular location: Cytoplasm; Membrane; Cell projection, dendritic spine
Subcellular location (Human Protein Atlas): Cytosol; Nucleoplasm
Pathways (Reactome):
Disease: ALK mutants bind TKIs; Constitutive Signaling by Aberrant PI3K in Cancer; Signaling by ALK fusions and activated point mutants; Signaling by cytosolic PDGFRA and PDGFRB fusion proteins
Signal Transduction: Extra-nuclear estrogen signaling; PI5P, PP2A and IER3 Regulate PI3K/AKT Signaling; PIP3 activates AKT signaling
Gene Ontology:
Molecular function: armadillo repeat domain binding; nuclear estrogen receptor binding; protein binding; protein phosphatase 2A binding; protein-containing complex binding; calmodulin binding; protein-macromolecule adaptor activity
Biological process: negative regulation of cell population proliferation; Wnt signaling pathway; bicellular tight junction assembly; dendrite development; locomotory behavior; regulation of hippo signaling; regulation of signal transduction
Cellular component: bicellular tight junction; FAR/SIN/STRIPAK complex; cytoplasm; cytosol; dendrite; dendritic spine; membrane; neuronal cell body; postsynapse; postsynaptic density; postsynaptic membrane; cell junction
Genetic constraint (gnomAD): Loss-of-function variants: 42 observed, 79.16 expected, observed/expected ratio (o/e) 0.53, 90% interval 0.41 to 0.69. The synonymous counts are far from expectation, so gnomAD's model fits this gene poorly and the ratio says little. Missense variants: 951 observed, 880.79 expected, observed/expected ratio (o/e) 1.08, 90% interval 1.02 to 1.14. Synonymous variants: 414 observed, 329.04 expected, observed/expected ratio (o/e) 1.26, 90% interval 1.16 to 1.37.
Homologues: Orthologues: chimpanzee STRN (99% identical), macaque STRN (99% identical), pig STRN (98% identical), guinea pig STRN (97% identical), mouse Strn (97% identical), rat Strn (97% identical), dog STRN (95% identical), rabbit STRN (87% identical), tropical clawed frog strn (82% identical), zebrafish strn (74% identical), Drosophila melanogaster Cka (47% identical), Caenorhabditis elegans cash-1 (37% identical). Paralogues in human: STRN3 (64% identical), STRN4 (51% identical).
Diseases named in the same sentence as STRN in open-access papers:
STRN is named in the same sentence as 54 diseases in open-access papers, as found by Europe PMC text mining. Sharing a sentence is not in itself a finding about the gene and the disease. The quoted sentences say what the papers report.
thyroid cancer (10 papers, 2014 to 2025). "Unlike the diverse ALK fusion variants seen in other cancers, thyroid cancer cells specifically exhibit STRN-ALK fusions, which encode for striatin." (PMID 40363930, 2025). "The STRN-ALK fusion is a genetic alteration implicated in thyroid cancer, leading to the downregulation of sodium-iodide symporter (NIS), a key factor in radioactive iodine (RAI) refractoriness." (PMID 40363930, 2025). "In contrast to different ALK translocation fusions, identified in other tumor types, the STRN-ALK fusions encoding for striatin were identified in thyroid cancer cells." (PMID 29455653, 2018). "Increased expression and activation of YAP1 have been reported in thyroid cancer cell lines and tissues, making the coiled-coil region of STRNs a potential therapeutic target in cancers with STRN-ALK fusion." (PMID 38201504, 2023). "The anaplastic lymphoma kinase (ALK) fusion with striatin (STRN) was identified in patient derived thyroid cancer cells in 2014, which leads to continuous MAPK signaling through MEK activation." (PMID 34335481, 2021). "The crucial role of the STRN-ALK fusion in the development of dedifferentiated thyroid cancer have been highlighted by the development of a transgenic mouse model with phenotypic features recapitulating a poor differentiated human tumor." (PMID 32235612, 2020). "One of the ALK rearrangements described involves the striatin (STRN) gene observed more commonly in thyroid cancers." (PMID 25276134, 2014). "This fusion could lead to constitutive activation of ALK kinase fusion via dimerization mediated by the coiled‐coil domain of STRN as proved in thyroid cancer both in vitro and in vivo." (PMID 34541785, 2021). "In thyroid cancers, ALK fusions, most frequently the STRN-ALK fusion, are detected in PTC and, with higher frequency, in PDTC and ATC." (PMID 32235612, 2020). "Consistent with previous studies, we detected EML4–ALK fusions in ~1% (5/513) of lung adenocarcinoma samples, multiple ALK fusions, including a single STRN–ALK fusion, in thyroid cancer (3/498) and one in papillary renal carcinoma." (PMID 25204415, 2014). "Previously reported fusion genes in thyroid cancer, ETV6–NTRK3 (4.80% in PTC), CCDC6–RET (2.40% in PTC), NCOA4–RET (0.80% in PTC), SQSTM1–NTRK1 (0.80% in PTC), STRN–ALK (0.80% in PTC), and PAX8–PPARG (0.80% and 1.82% in PTC and FTN, respectively), were also identified." (PMID 27494611, 2016).
arrhythmogenic right ventricular cardiomyopathy (5 papers, 2011 to 2024). "A small deletion in the 3’ untranslated region of striatin that leads to lower levels of striatin mRNA was recently implicated in a canine model of arrhythmogenic right ventricular cardiomyopathy." (PMID 28333931, 2017). "Moreover, a small deletion in the 3' untranslated region of striatin that leads to lower levels of striatin mRNA was recently implicated in a canine model of arrhythmogenic right ventricular cardiomyopathy." (PMID 21985334, 2011). "The objective of this paper was to investigate by pedigree-based genetic means the origins and inheritance of arrhythmogenic right ventricular cardiomyopathy (ARVC) in UK Boxers and assess the role of the proposed causal mutation in the gene, Striatin (STRN)." (PMID 25661582, 2015). "Further evidence for a role for STRN in heart failure comes from boxer dogs with arrhythmogenic right ventricular cardiomyopathy (ARVC) and heart failure, resulting from an 8 bp deletion in the 3′UTR of STRN and reduced STRN expression." (PMID 38718356, 2024). "In Boxer dogs from US, a mutation in the striatin gene was found associated with arrhythmogenic right ventricular cardiomyopathy (ARVC) but could not explain all cases of ARVC." (PMID 22761652, 2012).
hepatocellular carcinoma (4 papers, 2020 to 2025). A malignant tumor that arises from hepatocytes. "The most recent research from Liu and colleagues found that aberrantly high expression of circTNPO3 might exacerbate the malignant biological behavior of hepatocellular carcinoma via classical ceRNA mechanism, circTNPO3/miR-199b-5p/STRN axis." (PMID 40822457, 2025). "Then, we preliminarily confirmed that STRN could reverse the effect of STK25 depletion through AMPK/ACC1 pathway, which suggested that STK25 enhances hepatocellular carcinoma progression through the STRN/AMPK/ACC1 pathway." (PMID 34986838, 2022). "STRN participates in the progress of hepatocellular carcinoma by inducing EMT." (PMID 35277199, 2022). "A STRN-ALK fusion protein has been recently identified as a potential therapeutic target in multiple cancers; however, the role of STRN alone in regulating the biological function of hepatocellular carcinoma (HCC) remains unclear." (PMID 32280692, 2020).
lung adenocarcinoma (4 papers, 2014 to 2025). A carcinoma that arises from the lung and is characterized by the presence of malignant glandular epithelial cells. "ALK-rearranged carcinomas are less frequent than those with RET or NTRK rearrangements, and typically involve fusion with partner genes, such as STRN (encoding striatin) or EML4 (also involved in lung adenocarcinoma)." (PMID 41175860, 2025). "Here, we reported a case of lung adenocarcinomas with brain metastasis, harboring STRN-ALK fusion, responded well to ensartinib." (PMID 36290807, 2022).
lung carcinoma (4 papers, 2020 to 2024). "As for this latter, apart from the mentioned STRN::NTRK fusions in adult fibrosarcomas, STRN::ALK fusions have been identified in some thyroid and lung carcinomas, where they are thought to lead to ligand-independent activation of ALK kinase." (PMID 39582973, 2024). "STRN, a calmodulin-binding protein member, is a partner of ALK protein, and its fusion protein, which was identified in thyroid and lung carcinoma, leads to constitutive activation of ALK tyrosine kinase via dimerization mediated by the coiled-coil domain of STRN." (PMID 31936239, 2020). "Other less common rearrangements detected in lung cancer patients include KIF5B-ALK (kinesin family member 5B-ALK), TFG (trafficking from ER to golgi regulator)-ALK, KLC1 (kinesin light chain-1)-ALK, PTPN3 (protein tyrosine phosphatase non-receptor type 3)-ALK, STRN (striatin)-ALK." (PMID 39457620, 2024).
breast carcinoma (3 papers, 2012 to 2017). "Of the network genes ESR2, STRN and ANKS1B exhibited recurrent disrupting alleles among cancer cases, emphasizing their potential role in breast cancer predisposition." (PMID 22737080, 2012).
colorectal cancer (3 papers, 2020 to 2022). A primary or metastatic malignant neoplasm that affects the colon or rectum. "STRN represented the second most common ALK fusion partner, and were detected in two cases of colorectal cancer and one case of hepatobiliary cancer." (PMID 36369474, 2022). "The STRN-ALK fusion gene, a new driver gene, has been found in multiple cancers, including thyroid cancer, non-small-cell lung cancer (NSCLC), colorectal cancer, and renal carcinoma." (PMID 32280692, 2020). "The rare STRN-ALK fusion has been found in several different cancer types, including papillary thyroid cancer, NSCLC, colorectal cancer, and renal carcinoma." (PMID 32280692, 2020).
heart failure (3 papers, 2022 to 2024). Inability of the heart to pump blood at an adequate rate to meet tissue metabolic requirements. "SNPs in the STRN gene have been linked to regulation of blood pressure and the development of heart failure using GWAS, but there are some difficulties with interpretation." (PMID 38718356, 2024). "To assess which of the striatin isoforms is most likely to promote human heart failure, we mined an RNASeq database of heart samples from patients with dilated cardiomyopathy (DCM; n =97) compared with normal controls (n=108)." (PMID 38718356, 2024). "Consistent with this concept, reduced expression of STRN in boxer dogs is associated with ARVC and heart failure, both of which are associated with a higher risk of life-threatening ventricular arrhythmia and poor prognosis." (PMID 38718356, 2024). "Nevertheless, SNPs in the STRN gene are also linked to increased blood pressure (rs2540923, rs3770770) in addition to QRS/PR interval (rs3770770, rs17496249), hypertrophic cardiomyopathy and heart failure (rs2003585)." (PMID 38718356, 2024). "This study only considers the role of STRN and STRN3 in the early stages of cardiac remodelling induced by AngII, not the later stages associated with heart failure and decreased ejection fraction." (PMID 38718356, 2024). "Thus, although STRN and STRN3 have a similar profile overall with up-regulation in disease, STRN4 may have more specific and selective roles in different forms of heart failure." (PMID 38718356, 2024).
non-small cell lung carcinoma (3 papers, 2020 to 2022). A group of at least three distinct histological types of lung cancer, including non-small cell squamous cell carcinoma, adenocarcinoma, and large cell carcinoma. "STRN-ALK fusion is a rare ALK rearrangement identified in non-small cell lung cancer (NSCLC) patients." (PMID 36290807, 2022). "In non-small cell lung cancer (NSCLC) EML4-ALK is one of the more common fusion events, but there are other reported variants of ALK fusion proteins that do not involve the EML4 gene such as KIF5B-ALK, STRN-ALK, HIP1-ALK, VCL-ALK, NPM-ALK, and TGF-ALK2–5." (PMID 35233056, 2022).
renal carcinoma (3 papers, 2020 to 2025). A carcinoma arising from the epithelium of the renal parenchyma or the renal pelvis. "Similarly, STRN mutations can generate STRN/ALK fusion proteins, previously linked to metastatic progression in colorectal, breast, and renal cancers." (PMID 40486961, 2025). "STRN‐ALK fusion has been reported in multiple cancers including thyroid, colorectal, and renal cancer, and is related to aggressive features such as distant and lymph node metastasis." (PMID 33960639, 2021).
depression (2 papers, 2017 to 2024). "The relationship between depression/anxiety severity and genes expression profiles (STRN, CD84 and CTNS) in SSD patients." (PMID 28333931, 2017). "The relationship between depression/anxiety severity and genes expression profiles (STRN, CD84 and CTNS) in MDD patients." (PMID 28333931, 2017).
hypertrophic cardiomyopathy (2 papers, 2024). A condition in which the myocardium is hypertrophied without an obvious cause. "Given the link between STRN and ARVC in boxer dogs and SNPs in the STRN gene to hypertrophic cardiomyopathy, it will be important to conduct additional studies to assess possible arrhythmias in mice with STRN knockdown." (PMID 38718356, 2024).
metanephric adenoma (2 papers, 2019 to 2024). A benign, well-circumscribed renal cortical neoplasm affecting females more often than males. "Additionally, ALK::STRN and ALK::PLEKHA7 gene fusions have been described in tumors mimicking metanephric adenoma, corroborating the notion that gene fusion partners might impact morphology and even clinical outcomes." (PMID 37999735, 2024).
pancreatic tumors (2 papers, 2023 to 2025). "Some of these fusions, like Echinoderm Microtubule-Associated Protein-Like 4 (EML4)-ALK and Striatin (STRN)-ALK, may be found in pancreatic tumors." (PMID 41374970, 2025).
C. perfringens infection (1 paper, 2021). "The up-regulation of striatin after C. perfringens infection suggests that the host may increase processing activities to maintain the integrity of cell adhesion and reduce the negative impact caused by C. perfringens challenge." (PMID 34959561, 2021).
cardiac hypertrophy (1 paper, 2024). "The data indicate that cardiomyocyte striatin is required for early remodelling of the heart by AngII and identify the striatin-based STRIPAK system as a signalling paradigm in the development of pathological cardiac hypertrophy." (PMID 38718356, 2024). "Our data implicate cardiomyocyte STRN in cardiac hypertrophy, but provide limited insight into the mechanism of action." (PMID 38718356, 2024). "Nevertheless, the data in this study clearly identify striatin-based STRIPAKs as a novel signalling paradigm in the development of pathological cardiac hypertrophy." (PMID 38718356, 2024). "Thus, striatin-based STRIPAKs are required for cardiomyocyte and cardiac hypertrophy in AngII-induced hypertension." (PMID 38718356, 2024). "Thus, although the data suggest that inhibiting STRN will reduce cardiac hypertrophy induced by AngII, STRN potentially acts at the core of multiple complexes that regulate different GCKs, and one or more of these GCKs may be involved." (PMID 38718356, 2024). "Potential significance of results to human health and disease: STRN-based STRIPAKs represent a novel signalling paradigm in the development of pathological cardiac hypertrophy, and modulating this system may provide therapeutic options for managing the cardiac effects of hypertensive heart disease." (PMID 38718356, 2024).
cerebral cavernous malformation (1 paper, 2011). A disorder characterized by malformations in the structure of the capillaries in the brain. "The CCM3 protein found in striatin complexes is one of three gene products mutated in cerebral cavernous malformation, a common type of angioma." (PMID 21985334, 2011). "Striatin, a putative protein phosphatase 2A (PP2A) B-type regulatory subunit, is a multi-domain scaffolding protein that has recently been linked to several diseases including cerebral cavernous malformation (CCM), which causes symptoms ranging from headaches to stroke." (PMID 21985334, 2011).
Hyperkeratosis (1 paper, 2022). Hyperkeratosis is a histopathological term defining a thickened stratum corneum and may be present in many different skin conditions, with many possible overlaps. "Among these genes, SQLE, STRN, EIF4, and MYO1B expression was increased in patients with hyperkeratosis, parakeratosis, and acanthosis thickening." (PMID 35277199, 2022). "Patients with hyperkeratosis and parakeratosis, acanthosis thickening had increased expression of 13 the same genes, including SQLE, STRN, EIF4E, and MYO1B." (PMID 35277199, 2022). "Therefore, we speculate that AP-1 upregulates the expression of SQLE, STRN, EIF4E, and MYO1B; it brings keratinocytes EMT, which further mediates hyperkeratosis with parakeratosis and acanthosis thickening." (PMID 35277199, 2022).
Hypertension (1 paper, 2024). The presence of chronic increased pressure in the systemic arterial system. "Our studies assessed the effects of STRN deletion only in young male mice and in a context of AngII-induced hypertension using a dose of 0.8 mg/kg/d." (PMID 38718356, 2024).
metastasis (1 paper, 2025). The spread or migration of cancer cells from one part of the body (where they first appeared) to another. "A 66-year-old man with IMT bone metastasis accompanied by GCC2-ALK fusion and another man with pulmonary IMT underwent postoperative disease progression with STRN-ALK fusion both obtained PR following treatment with ensartinib." (PMID 40386559, 2025).
Myocardial fibrosis (1 paper, 2021). "MiR-21 can inhibit apoptosis and inflammation by targeting KBTBD7, regulate angiogenesis through STRN/NOS3, and promote myocardial fibrosis through the TGF-β/Smad7 signaling pathway." (PMID 35111829, 2021).
myocarditis (1 paper, 2015). Myocarditis is a condition that is characterized by inflammation of the heart muscle (myocardium). "As STRN plays a role in the cardiomyocyte, it may interact with the (unknown) ARVC mutation to trigger its development, as may exercise, myocarditis, stress or concurrent heart conditions." (PMID 25661582, 2015).
psoriasis (1 paper, 2022). An autoimmune condition characterized by red, well-delineated plaques with silvery scales that are usually on the extensor surfaces and scalp. "In this regard, it is interesting to note that AP-1 upregulates the gene expression of SQLE, STRN, EIF4E, and MYO1B might to promote the abnormality of keratinocytes and immune system to mediate the occurrence of psoriasis." (PMID 35277199, 2022).
soft tissue tumors (1 paper, 2023). "To date, there are approximately 42 partner genes involving NTRK2 rearrangement, and only STRN and RBPMS are identified in the fusion with NTRK2 in adult soft tissue tumors." (PMID 37865792, 2023). "To date, only STRN and RBPMS are identified in the fusion with NTRK2 in adult soft tissue tumors." (PMID 37865792, 2023).
thyroid nodule (1 paper, 2025). A small circumscribed mass in the THYROID GLAND that can be of neoplastic growth or non-neoplastic abnormality. "Therefore, the targets widely recognized and recommended by scholars at home and abroad were selected to compose a 6-gene test panel for thyroid nodule diagnosis, including BRAF V600E mutation, TERT mutation, and gene fusions (CCDC6-RET, NCOA4-RET, ETV6-NTRK3, EML4-NTRK3, STRN-ALK, and PAX8/PPARG)." (PMID 40586006, 2025).